SMG7 (SMG7 nonsense mediated mRNA decay factor)
Description:
Plays a role in nonsense-mediated mRNA decay. Recruits UPF1 to cytoplasmic mRNA decay bodies. Together with SMG5 is thought to provide a link to the mRNA degradation machinery involving exonucleolytic pathways, and to serve as an adapter for UPF1 to protein phosphatase 2A (PP2A), thereby triggering UPF1 dephosphorylation.
Synonyms: C1orf16; EST1C; KIAA0250; SGA56M; SMG-7
Tractability: PROTAC: ubiquitination databases record sites on it; its protein half-life has been measured.
Gene: Protein-coding gene on chromosome 1 (183,471,957 to 183,598,246, forward strand). Ensembl gene ENSG00000116698.
Subcellular location: Cytoplasm; Nucleus
Subcellular location (Human Protein Atlas): Cytosol; Nucleoli; Basal body; Nuclear speckles; Vesicles
Pathways (Reactome):
Metabolism of RNA: Nonsense Mediated Decay (NMD) enhanced by the Exon Junction Complex (EJC)
Gene Ontology:
Molecular function: protein binding; protein phosphatase 2A binding; telomeric DNA binding; telomerase RNA binding
Biological process: mRNA export from nucleus; nuclear-transcribed mRNA catabolic process, nonsense-mediated decay; regulation of dephosphorylation
Cellular component: cytoplasm; cytosol; nonsense-mediated decay complex; nuclear speck; nucleolus; nucleus; telomerase holoenzyme complex
Genetic constraint (gnomAD): Loss-of-function variants: 33 observed, 118.78 expected, observed/expected ratio (o/e) 0.28, 90% interval 0.21 to 0.37. The upper end of that interval is the gene's LOEUF score, 0.37, which puts it in group 1 of 6, group 1 being the genes least tolerant of losing a copy. Missense variants: 988 observed, 1,281.4 expected, observed/expected ratio (o/e) 0.77, 90% interval 0.73 to 0.81. Synonymous variants: 429 observed, 470.45 expected, observed/expected ratio (o/e) 0.91, 90% interval 0.84 to 0.99.
Homologues: Orthologues: pig SMG7 (97% identical), macaque SMG7 (96% identical), rat Smg7 (95% identical), guinea pig SMG7 (93% identical), chimpanzee SMG7 (93% identical), mouse Smg7 (92% identical), dog SMG7 (91% identical), rabbit SMG7 (84% identical), tropical clawed frog smg7 (73% identical), zebrafish smg7 (65% identical), Caenorhabditis elegans smg-7 (11% identical). Paralogues in human: SMG5 (17% identical).
Diseases named in the same sentence as SMG7 in open-access papers:
SMG7 is named in the same sentence as 28 diseases in open-access papers, as found by Europe PMC text mining. Sharing a sentence is not in itself a finding about the gene and the disease. The quoted sentences say what the papers report.
breast carcinoma (4 papers, 2020 to 2024). "The knockdown of SMG7 in breast cancer cells decreased the effectiveness of TNFα-mediated cell death." (PMID 37349371, 2023). "Forced knockdown of SMG7 by siRNA (siSmg7) in NIH 3T3 and MCF‐7 breast cancer cells restored viability upon TNFα treatment." (PMID 32602581, 2020).
Infertility (3 papers, 2013 to 2024). "Compared to Wt N. benthamiana plants, the smg7 and upf3 mutants showed obvious developmental defects, including dwarfing in their later growth stages and infertility." (PMID 39189522, 2024). "Identifying a mutation, twice independently, in the gene for centromeric histone CENH3 that partially rescues infertility of smg7-6 plants came as a surprise." (PMID 34591845, 2021).
colorectal cancer (2 papers, 2017 to 2023). A primary or metastatic malignant neoplasm that affects the colon or rectum. "Genes implicated in the NMD pathway, such as Upf1, Upf2, Smg1, Smg6, and Smg7, are expressed in higher levels in colorectal cancer (CRCs) with microsatellite stability, and promote tumor growth in xenograft models." (PMID 37888706, 2023).
lung carcinoma (2 papers, 2016 to 2024). "Using immunofluorescence, we found that SMG7 is localized in both the nucleus and cytoplasm when transiently expressed in human lung cancer H1299 cells." (PMID 27462439, 2016).
prostate carcinoma (2 papers, 2020 to 2024). A carcinoma that arises from epithelial cells of the prostate gland. "SMG7 has also been identified in a large cohort to be associated with prostate cancer." (PMID 32602581, 2020). "Indeed, NF‐κB therapeutics for prostate cancer, for which SMG7 was found to be a novel risk factor, shows promise in modulating tumorigenesis and progression." (PMID 32602581, 2020).
viral infection (2 papers, 2019 to 2024). "Nonsense‐mediated RNA decay (NMD) factors SMG7 and UPF3 recognize viral specific RNA features to mediate viral RNA degradation for restricting virus infection." (PMID 39189522, 2024).
asthma (1 paper, 2023). "Compared with the control group, the expression of Fos, Myl9 and Tlr4 in the asthma model was increased, while the expression of Smg7, Sumo2 and Stat5a was decreased." (PMID 36726128, 2023). "Additionally, based on the previously published literatures on asthma and inflammation, we screened out down-regulated genes, such as Smg7, Sumo2, and Stat5a, and up-regulated genes, such as Myl9, Fos and Tlr4." (PMID 36726128, 2023). "Our data showed that the gene expression and protein level of SMG7 and co-expressed lncRNA NONMMUT032848 was reduced in the asthma model of mice." (PMID 36726128, 2023).
Autoimmunity (1 paper, 2021). The occurrence of an immune reaction against the organism's own cells or tissues. "The long 3′ UTR is a typical characteristic of nonsense-mediated mRNA decay (NMD) target, and RPS6 is required for autoimmunity in NMD-deficient mutant smg7." (PMID 33924988, 2021).
Burkitt lymphoma (1 paper, 2020). A rare form of malignant mature B-cell non-Hodgkin lymphoma. "SMG7 is highly expressed in cells derived from Burkitt's lymphoma." (PMID 32602581, 2020).
colorectal adenocarcinoma (1 paper, 2021). The most common type of colorectal carcinoma. "To corroborate this finding, we generated SMG7 knockouts in human colorectal adenocarcinoma DLD1 cells using CRISPR-Cas9-mediated gene editing." (PMID 33820915, 2021).
Insulin resistance (1 paper, 2019). Increased resistance towards insulin, that is, diminished effectiveness of insulin in reducing blood glucose levels.
lymphoma (1 paper, 2017). A malignant (clonal) proliferation of B- lymphocytes or T- lymphocytes which involves the lymph nodes, bone marrow and/or extranodal sites. "SMG7 (also known as Breast Cancer-Associated Antigen SGA-56 M) has been associated with cancer and is strikingly absent from a panel of 11 of 12 lymphoma samples tested for SMG7 antibody staining suggesting that, as shown in our experiments, cells are resistant to apoptosis stimuli." (PMID 29178829, 2017).
sarcoma (1 paper, 2023). A usually aggressive malignant neoplasm of the soft tissue or bone. "As our pretreatment experiments showed that SMG7 plays an important role in the tumor growth of our sarcoma cells, we wanted to explore the viability of targeting SMG7 in vivo." (PMID 37349371, 2023).
sarcopenia (1 paper, 2022). Progressive decline in muscle mass due to aging which results in decreased functional capacity of muscles. "As SMG7 is linked with telomerase reverse transcriptase (TERT), sarcopenia may be related to muscle cell senescence via microRNA-19533." (PMID 35241739, 2022). "The eQTL analysis for muscle mass using GTEx datasets showed that RPS10, NUDT3, NCF2, SMG7, and ARPC5 were differentially expressed in the muscle tissue for sarcopenia." (PMID 35241739, 2022).
cancer (9 papers, 2017 to 2025). A tumor composed of atypical neoplastic, often pleomorphic cells that invade other tissues. "Cancer-derived mutations in SMG7 lack any significant effect over the interaction interface with the SMG1 or UPF2 proteins." (PMID 38542156, 2024). "Overall, our data show that the loss of SMG7 induces a strong anti-cancer effect both in vitro and in vivo." (PMID 37349371, 2023). "This implies that cancers associated with constitutive NF‐κB activation are more likely to be susceptible to SMG7 levels." (PMID 32602581, 2020). "If SMG7 falls into the cancer fitness gene category, then it would, ideally, be exploited by cancer cells but be dispensable for non-transformed cells under homeostatic conditions." (PMID 37349371, 2023). "While there is evidence to support the idea that NMD factors act in either a pro- or anti-tumorigenic role in divergent cancers, the necessity for SMG7 in transformation is unexplored." (PMID 37349371, 2023). "Strikingly, CYLD and SMG7 expression showed a near‐universal correlation in diverse human cancer cell lines and clear cell renal cell carcinoma patient survival." (PMID 32602581, 2020). "To further validate our bioinformatic approach we selected two other circRNAs deregulated in cancer, SMG7 and RPN2." (PMID 29262850, 2017). "Our data evinces SMG7 as a prospective cancer fitness gene in RMS and that disrupting SMG7 function may be tolerable and provide a therapeutic benefit for patients with STS." (PMID 37349371, 2023). "The ability to generate several, unique STSs provides additional benefit as STSs are a very heterogeneous group of cancers, and SMG7 may play different roles in different histological subtypes." (PMID 37349371, 2023). "In total, current evidence suggests that SMG7 is a part of a complex pathway that may be a tool cancer cells utilize for a proliferative, survival, stress-response, or metastatic advantage." (PMID 37349371, 2023). "In this study, we have shown that SMG7 behaves similarly to a cancer fitness gene." (PMID 37349371, 2023). "SMG7 may play a pro-tumorigenic role in our cells by downregulating several anti-cancer genes." (PMID 37349371, 2023). "In cancers such as microsatellite instability (MSI) cancers, NMD has been shown, on the contrary, to be activated through increased expression of certain NMD-factor genes: UPF1, UPF2, SMG1, SMG6, and SMG7." (PMID 35052820, 2022). "This positive relationship between SMG7 and CYLD was found to be widely conserved in human cancer cell lines and renal carcinoma samples from The Cancer Genome Atlas." (PMID 32602581, 2020). "Our data supports SMG7 as a cancer fitness gene under (II) and (III), as we showed SMG7 was critical to maintain RMS growth and survival (II) but was dispensable for MEFs and adult mice (III); however, the role of SMG7 in transformation (I) is currently unknown." (PMID 37349371, 2023). "In the HGSOC data set, the mtSNVs were called in most cancer and noncancer cells, and some fusion calls were expressed in most clones or subclones (P2: IGF2BP2::TESPA1, P1: SMG7::CH507-513H4.1, etc.), making them ideal variations for cell type reannotation and clustering." (PMID 40107722, 2025). "The role that SMG7 and other NMD factors may play in cancer is a relatively novel and burgeoning field." (PMID 37349371, 2023).
tumor (7 papers, 2018 to 2025). "The loss of SMG7 significantly decreased tumor growth in both of the clonal populations, as evidenced by their average tumor masses." (PMID 37349371, 2023). "To further analyze and categorize the effects that the loss of SMG7 has on tumor growth in our RMS cells, we repeated the 2-day pretreatment-experiment using a smaller fraction of tumor and clonal cells." (PMID 37349371, 2023). "To analyze the effects of SMG7 loss on cell proliferation, we performed a 5-Chloro-2'-deoxyuridine (CldU) stain of our tumor and clonal cells 6 days after treatment." (PMID 37349371, 2023). "The loss of SMG7 induced a significant increase in the mRNA level of p21 in our tumor (ΔCt—EtOH 5.407 ± 0.2466 & 4-OHT 4.329 ± 0.3210; P = 0.0374) and clone 5 (ΔCt—EtOH 6.239 ± 0.4141 & 4-OHT 4.986 ± 0.2477; P = 0.0408) cells, as well as a clear upregulation of p21 protein." (PMID 37349371, 2023). "We hypothesize the anti-tumor effects seen following SMG7 knockout in our RMS cells result from the loss of NMD and its mediated suppression of PTC+-transcripts, cell cycle arrest genes, and pro-apoptotic genes." (PMID 37349371, 2023). "We have observed that SMG7 is required for targeting GADD45b and the tumor suppressor lncRNA GAS5 for degradation in our cells." (PMID 37349371, 2023). "To test the effects of SMG7 loss on our RMS cells, we induced SMG7 knockout by treating our tumor and clonal cells with 4-hydroxytamoxifen (4-OHT), or ethanol (EtOH) as a vehicle control, and observed the effects." (PMID 37349371, 2023). "We elected to go with a GEMM as we are interested in the role of SMG7 in both tumorigenesis and the tumor microenvironment." (PMID 37349371, 2023). "The loss of SMG7 significantly decreased the tumor growth of our RMS cells, as exhibited by a ~ 54% lower average tumor mass in the 4-OHT treated group (EtOH 1.675 g ± 0.1264 & 4-OHT 0.7728 g ± 0.09637; P = 0.000007)." (PMID 37349371, 2023). "The data highlight a novel and specific regulation of oncogenic factors by SMG7 and pinpoint a composite tumor suppressor role in response to TNF." (PMID 32602581, 2020). "Yet, the functional role of downstream targets of SMG7 with respect to TNFα and tumor biology is poorly understood." (PMID 32602581, 2020). "Expression levels for NMD-related factors (UPF1, UPF2, UPF3A, UPF3B, SMG1, SMG2, SMG6, and SMG7) were calculated from microarray-derived datasets of primary tumor samples (n = 40 MSI, n = 48 MSS) and matched normal colon samples (n = 95)." (PMID 30228267, 2018). "To analyze the importance of SMG7 for tumor growth, we performed several in vivo experiments." (PMID 37349371, 2023). "As the loss of SMG7 significantly decreased the fitness of our RMS cells in vitro, we then turned to in vivo studies to test if the loss of SMG7 would have a similar inhibitory phenotype on RMS tumor growth." (PMID 37349371, 2023). "Our study reflects the crucial role that SMG7 plays in one RMS tumor population." (PMID 37349371, 2023). "The results indicate a composite tumor suppressor role for SMG7 in response to TNF." (PMID 32602581, 2020). "The Tam treated group had an average tumor mass that was ~ 63% lower than the average tumor mass of the CO treated group (CO 0.1998 g ± 0.0382 & Tam 0.0725 g ± 0.0178; P = 0.0023), giving credence to the possibility of targeting SMG7 function for STS treatment." (PMID 37349371, 2023). "Expression-based clustering of cells for the patient-1 tumor sample resolved two HGSOC cell clusters, with fusion RAPGEF5::AGMO evident in tumor cells largely clustered separately from cells expressing SMG7::CH507-513H4.1 and GS1-279B7.2::GNG4, potentially reflecting tumor heterogeneity." (PMID 40086881, 2025). "Sequencing of the patient-1 tumor sample yielded 497 total cells, with 92 cells (19%) identified as HGSOC cells, from which we identified only four somatic fusion transcripts: SMG7::CH507-513H4.1 (26 cells), RAPGEF5::AGMO (6 cells), NTN1::CDRT15P2 (five cells), and GS1-279B7.2::GNG4 (five cells)." (PMID 40086881, 2025).
tumor (continued). "Sequencing of the Patient-1 tumor sample yielded 497 total cells, with 92 cells (19%) identified as HGSOC cells, from which we identified only four somatic fusion transcripts: SMG7::CH507–513H4.1 (26 cells), RAPGEF5—AGMO (6 cells), NTN1--CDRT15P2 (5 cells), and GS1–279B7.2--GNG4 (5 cells)." (PMID 38464114, 2024). "These tumor studies show that SMG7 is required for the full capacity tumor growth of our RMS cells and, without SMG7, tumors exhibit increased levels of apoptosis and significantly inhibited tumor growth." (PMID 37349371, 2023). "Our mouse studies showed that deletion of SMG7 significantly decreased tumor growth of our RMS cells and that SMG7 was dispensable for adult mouse survival, which is in contrast to UPF2, where the conditional knockout of UPF2 in adult mice quickly led to death." (PMID 37349371, 2023). "Deletion of SMG7, induced by 4-OHT treatment, significantly decreased tumor growth of our RMS cells, regardless of the number of tumor cells we initially injected." (PMID 37349371, 2023).
infection (2 papers, 2020 to 2023). The state of being infected such as from the introduction of a foreign agent such as serum, vaccine, antigenic substance or organism. "Similarly, SMG5 and SMG7 were significantly decreased at 6 compared to that at 3 h after infection, while at 9 h post-infection, they were significantly higher than at 1 and 6 h." (PMID 36768954, 2023). "NMD inhibition (+U1D) and PEMV2 infection resulted in increased transcript levels for SMG7, SMG9, UPF1, UPF3, and CASC3, whereas HA-p26 expression increased transcript levels only for SMG7, SMG9, and UPF3." (PMID 32156817, 2020). "We found a significant decrease of DExH-Box Helicase 34 (DHX34), suppressor with morphogenetic effect on genitalia 5 (SMG5), and SMG7 expression at 6 h post-infection, followed by a significant increase of these genes and also UPF1 and UPF2 at 9 h post-infection." (PMID 36768954, 2023).
neurodegenerative disease (1 paper, 2023). A disorder of the central nervous system characterized by gradual and progressive loss of neural tissue and neurologic function. "For example, Lnc_Smg7-mediated RNA degradation has been implicated in neurodegenerative diseases." (PMID 37106826, 2023).
SMG7 also shares sentences with these, for which no sentence is quoted: bacterial infections (1 paper); Cardiac-urogenital syndrome (1); colon cancer (1); gastric cancer (1); glioma (1); multiple myeloma (1); ovarian carcinoma (1); renal cell cancer (1); rhabdomyosarcoma (1); type 2 diabetes (1).